B3GALNT1 (beta-1,3-N-acetylgalactosaminyltransferase 1 (Globoside blood group))
Description:
Transfers N-acetylgalactosamine onto globotriaosylceramide. Plays a critical role in preimplantation stage embryonic development (By similarity).
Synonyms: Beta3Gal-T3; b3Gal-T3; B3GALT3; galT3; GLOB; B3GALANT1; 3-GalNAc-T1; 3-GalTase; GLCT3; Gb4Cer; P1; beta-1; beta-3-Gx-T3
Tractability: Antibody: UniProt predicts a signal peptide or a membrane-spanning region. PROTAC: its protein half-life has been measured.
Gene: Protein-coding gene on chromosome 3 (161,083,612 to 161,105,445, reverse strand). Ensembl gene ENSG00000169255.
Subcellular location: Golgi apparatus membrane
Subcellular location (Human Protein Atlas): Vesicles
Pathways (Reactome):
Metabolism: Glycosphingolipid biosynthesis
Gene Ontology:
Molecular function: galactosylgalactosylglucosylceramide beta-D-acetylgalactosaminyltransferase activity; N-acetyl-beta-D-glucosaminide beta-(1,3)-galactosyltransferase activity; hexosyltransferase activity
Biological process: glycosphingolipid biosynthetic process; oligosaccharide biosynthetic process; carbohydrate derivative metabolic process; glycoprotein biosynthetic process
Cellular component: Golgi membrane; membrane
Genetic constraint (gnomAD): Loss-of-function variants: 17 observed, 28.35 expected, observed/expected ratio (o/e) 0.6, 90% interval 0.41 to 0.9. The upper end of that interval is the gene's LOEUF score, 0.9, which puts it in group 3 of 6, group 1 being the genes least tolerant of losing a copy. Missense variants: 347 observed, 406.18 expected, observed/expected ratio (o/e) 0.85, 90% interval 0.78 to 0.93. Synonymous variants: 141 observed, 150.19 expected, observed/expected ratio (o/e) 0.94, 90% interval 0.82 to 1.08.
Homologues: Orthologues: macaque B3GALNT1 (99% identical), dog B3GALNT1 (96% identical), pig B3GALNT1 (96% identical), guinea pig B3GALNT1 (95% identical), mouse B3galnt1 (93% identical), rat B3galnt1 (92% identical), zebrafish b3galt10.1 (32% identical), zebrafish b3galt8 (30% identical), zebrafish b3galt10.2 (24% identical), Caenorhabditis elegans bre-5 (22% identical), Drosophila melanogaster brn (22% identical), Caenorhabditis elegans F21C10.3 (8% identical), and 1 more. Paralogues in human: B3GALT5 (34% identical), B3GALT1 (33% identical), B3GALT2 (31% identical), B3GNT4 (26% identical), B3GNT9 (26% identical), B3GNT7 (26% identical), B3GALT4 (24% identical), B3GNT2 (24% identical), B3GNT3 (24% identical), B3GNT6 (24% identical), B3GNT5 (24% identical), B3GALT9 (23% identical), and 3 more.
Diseases named in the same sentence as B3GALNT1 in open-access papers:
B3GALNT1 is named in the same sentence as 21 diseases in open-access papers, as found by Europe PMC text mining. Sharing a sentence is not in itself a finding about the gene and the disease. The quoted sentences say what the papers report.
Alzheimer disease (1 paper, 2025). A progressive, neurodegenerative disease characterized by loss of function and death of nerve cells in several areas of the brain leading to loss of cognitive function such as memory and language. "Two genes required for fibrillar tau uptake, B3GALNT1 and B3GNTL1, encode glycosyltransferases, and the cell surface proteoglycan, GPC5, identified in Alzheimer’s disease GWAS, is also required for fibrillar tau entry." (PMID 40790356, 2025).
steatosis (1 paper, 2015). Increased lipid within the cytoplasm of cells. "Adipose expression of B3galnt1, encoding for the enzyme beta-1,3-galactosyltransferase 3, was correlated with steatosis (r = 0.30 and p = 0.001)." (PMID 26067236, 2015).
cancer (6 papers, 2002 to 2025). A tumor composed of atypical neoplastic, often pleomorphic cells that invade other tissues. "B3GALNT1 is a galactosyl transferase, which is often reported to be upregulated in various cancers." (PMID 25521548, 2014). "However, the association between B3GALNT1 expression and cancer development and progression is not well discussed as well." (PMID 35582412, 2022). "The heatmap showed that the 15 CpG sites (located on B3GALNT1, C6orf97, FAM72A, FAM72B, LIFR, OSMR, ZNF264, and ZNF543) well‐distinguished CRC from adjacent normal tissues, WBCs, and 28 other types of cancer in TCGA, as well as 23 other types of cancer in GEO." (PMID 37649326, 2023). "Thus, B3GALNT1 might have a role in NSCLC progression, although no reports have demonstrated a specific relationship between B3GALNT1 and cancer." (PMID 25521548, 2014).
B3GALNT1 also shares sentences with these, for which no sentence is quoted: tumour (3 papers); glioma (2); lung carcinoma (2); atopic dermatitis (1); bladder cancer (1); brain tumour (1); cervical cancer (1); chronic granulomatous disease (1); Cirrhosis (1); colon cancer (1); ductal carcinomas (1); glioblastoma (1); infection (1); liver fibrosis (1); meningioma (1); neuroblastoma (1); non-small cell lung carcinoma (1); Salmonella Infections (1).